CHRNA9 (cholinergic receptor nicotinic alpha 9 subunit)
Diseases named in the same sentence as CHRNA9 in open-access papers (continued):
Sharing a sentence is not in itself a finding about the gene and the disease.
viral infection (1 paper, 2017). "As expected, with both α9-nAChR sgRNA_1 and α9-nAChR sgRNA_2 viral infection, mixed CHRNA9 sequences were located at the predicted genome cleavage sites (arrowhead)." (PMID 29163048, 2017).
tumor (11 papers, 2016 to 2025). "CHRNA9 knockdown induced a significant reduction in tumor volumes and tumor weights compared to the control group, which suggested α9 nAChR should be a useful therapeutic target for TNBC." (PMID 40563476, 2025). "Our experimental results demonstrated that overexpression of α9 nAChR protected tumor cells from erastin-induced ferroptosis and CHRNA9 knockdown would trigger the occurrence of ferroptosis in cancer cells." (PMID 40563476, 2025). "We first evaluated the in vivo anti-tumor effect of direct silencing CHRNA9 by shRNA in a TNBC xenograft model." (PMID 40563476, 2025). "Bioinformatics methods were utilized to analyze the differential expression of CHRNA9 between tumor samples and normal samples." (PMID 38495483, 2024). "The results of Western blot detection of the total CHRNA9 protein expression level in the samples showed, compared with the para-cancerous samples, the CHRNA9 protein expression level in the tumor samples increased." (PMID 38495483, 2024). "In our study, we identified three upregulated genes (CHRNB4, CHRNA6, and CHRNA9) of the whole CHRNs between tumor tissues and normal controls in three kinds of SCCs." (PMID 33304845, 2020). "CHRNA9 is a Nicotinic Receptor and is related to smoking-induced tumor formation." (PMID 34503106, 2021). "However, after nicotine exposure, the luciferase activity in the tumor region was dramatically reduced to 26.3% (blue) of the original level, indicating that nicotine strongly dissociated CHRNA9/ERBB2 complex formation in this animal model." (PMID 31311925, 2019). "Interestingly, in addition to CHRNA7, only a few other nAChR subunit genes modified their expression due to the effect of tobacco (CHRFAM7A, CHRNA5, CHRNA9) or to the degree of tumor differentiation (CHRNA5), but these changes only happen in SQC-L tumors." (PMID 28978081, 2017). "Finally, we found that ex-vivo pre-treatment of GSCs, expressing CHRNA1 and CHRNA9, with Atracurium Besylate significantly increased the survival of mice xenotransplanted with these cells, therefore suggesting that tumor initiating subpopulations have been reduced." (PMID 26575950, 2016). "HCC38 cells of stable CHRNA9 knockdown or control were injected into the dorsal flank of BALB/c nude mice and the tumor volumes were monitored." (PMID 40563476, 2025). "Conversely, CHRNA9 knockdown would completely reverse all this signaling, ultimately inhibiting TNBC tumor growth both in vitro and in vivo." (PMID 40563476, 2025). "Although few immune-related genes had a high expression in cold tumor, such as MMP8, most genes highly express in cold tumor are not so closely related to immune responses, including CGA, INHA, IBSP, and CHRNA9." (PMID 33816503, 2021). "However, we did find the expression of CHRNA1, CHRNA9, and CHRNB1 to be significantly upregulated in the GBM samples in comparison to the non-tumor samples." (PMID 31590360, 2019).
cancer (7 papers, 2011 to 2025). A tumor composed of atypical neoplastic, often pleomorphic cells that invade other tissues. "Previous evidence demonstrated that silencing the expression of α9 nAChR (α9 nicotinic acetylcholine receptor, encoded by CHRNA9 gene, in cancer cells resulted in a significant reduction in the levels of metastasis-related proteins, Slug and Vimentin." (PMID 40563476, 2025). "The expression level of CHRNA9 have been found to be elevated in malignant tumors and implicated in the advanced progression of colorectal cancer." (PMID 38495483, 2024). "These suggest that our SIM strategy is useful for identifying potential proteins associated with CHRNA9 in various cancer types." (PMID 31311925, 2019). "Multiple lines of evidence indicate that homopentameric nAChRs of CHRNA1, CHRNA3, CHRNA4, CHRNA5, CHRNA6, CHRNA7, and CHRNA9 are involved in cancer initiation and progression." (PMID 33603170, 2021). "Among them, CHRNA7 and CHRNA9 have been reported to be capable of inducing cancer stem cell-like cells (CSC) or cancer-initiating cells (CIC)." (PMID 33603170, 2021). "Next, we used our strategy to link the CHRNA9 community, comprising CHRNA9 and its interacting proteins, and 65 cancer-related pathways to construct CaMPNets based on TCGA RNA-seq data in 15 cancer types." (PMID 31311925, 2019). "CHRNA9 has been shown to be closely related to the occurrence and development of cancer." (PMID 38495483, 2024). "Similarly, the analysis of the expression levels of CHRNA9 in different types of cancer showed that the expression levels of CHRNA9 are increased in most types of cancer." (PMID 38495483, 2024). "Conversely, some CHRNA9 community-regulated pathways, such as cell cycle, adherens junction, and ErbB signaling, were related to cell growth and communication in more than six cancer types, reflecting commonalities across many human malignancies." (PMID 31311925, 2019). "Besides, the Venn diagram demonstrated that there were three mutual DEGs in all three cancers: CHRNB4, CHRNA9, and CHRNA6." (PMID 33304845, 2020).
myopathies (1 paper, 2025). "The sole downregulated gene in SM of female broiler chickens, cholinergic receptor nicotinic alpha 9 subunit (CHRNA9), has not yet been related to myopathies, but it was found to be expressed in immune cells and mostly in T cells, suggesting its potential role in inflammation and immune response." (PMID 40841884, 2025).
CHRNA9 also shares sentences with these, for which no sentence is quoted: Alzheimer disease (1 paper); autism spectrum disorder (1); autoimmune disease (1); bipolar disorder (1); hearing loss (1); major depressive disorder (1); neurological disorders (1); nicotine dependence (1); Parkinson disease (1); schizophrenia (1); scoliosis (1).